INS (insulin)
Diseases named in the same sentence as INS in open-access papers (continued):
Sharing a sentence is not in itself a finding about the gene and the disease.
Hypoglycemia (continued). "Given the risk of hypoglycemia associated with intensive insulin therapy, current recommendations include treating hyperglycemia after two consecutive glucose > 180 mg/dL with target levels of 140–180 mg/dL for most patients." (PMID 32690029, 2020). "The risk of hypoglycemia was higher among patients receiving insulin (RR 1.90; 95% CI 1.44 to 2.51)." (PMID 32489427, 2020). "The causes of hypoglycemia in AKT2 mutation are related to the activation of the insulin signalling pathway." (PMID 32157856, 2020). "Chronic kidney disease is a well-known risk factor for hypoglycemia, but the benefit of intensive insulin therapy for such patients is low." (PMID 33015194, 2020). "Congenital hyperinsulinism (CHI) is characterized by abnormal regulation of insulin secretion from the pancreas causing profound hypoketotic hypoglycemia." (PMID 33108363, 2020). "High insulin levels limit hepatic glucose mobilisation and increase muscle glucose disposal, thereby causing hypoglycaemia." (PMID 32533229, 2020). "In healthy volunteers, insulin-induced hypoglycemia caused a robust increase in basal ventilation and HVR, but the hyperglycemic clamp did not reproduce the same strong effects on ventilation." (PMID 32698380, 2020). "The studies with continuous glucose monitoring recognized GV as a risk factor for hypoglycemia in type 1 and insulin-treated type 2 diabetic subjects." (PMID 33217980, 2020). "Accordingly, in thisstudy, weight‐based dosing of insulin and a monitoring schedule was used to minimize the risk of hypoglycemia." (PMID 32149451, 2020). "Medium-acting insulin have the disadvantages of high variability, obvious peak effect, shorter duration, and high risk of hypoglycemia at night." (PMID 33167951, 2020). "The insulin skin patch system is designed to improve and sustain levels of basal insulin to lower the risk of hypoglycemia, as well as ensure greater patient compliance than injecting insulin equivalents." (PMID 32325974, 2020). "Previous studies have reported a significant risk of hypoglycemia as a complication of the management of hyperkalemia with insulin." (PMID 32149451, 2020). "A 2018 meta-analysis of tight insulin control found that maintenance of systemic glucose between 4.4 and 6.7 mmol/L using insulin led to a trend toward improved neurological improvement but increased the risk of developing hypoglycemia." (PMID 33100956, 2020). "We proposed a model for predicting hypoglycemia risk in patients with T2DM treated with intensive insulin therapy." (PMID 33015194, 2020). "Fourth, it is possible that hypoglycemia caused by sulphonylurea and insulin is linked to abnormalities in brain metabolism and a reduced walking speed." (PMID 32640726, 2020). "The CONCLUDE population represents a more accurate reflection of patients seen in clinical practices than most published insulin randomised controlled trials where individuals with hypoglycaemia risk factors are typically excluded." (PMID 31984443, 2020). "This drop in insulin secretion facilitates lipid and glucose mobilisation from stores outside of the muscle, while minimising the risk for hypoglycaemia as contraction-mediated glucose disposal increases." (PMID 32533229, 2020). "Meanwhile, with the stability of insulin dose titration and the patient's ability of handling the treatment adjustments, the risk of hypoglycemia reduces." (PMID 33224195, 2020). "Polypharmacy is one of the risk factors associated with hypoglycemia as well as a lower education level, ethnicity, irregular meals/malnutrition, insulin and sulfonylurea therapy, cognitive impairment, depression and frailty." (PMID 32518665, 2020). "We developed a clinical prediction tool to identify the risk of hypoglycemia in patients with T2DM who undergo insulin intensive therapy." (PMID 33015194, 2020).
Hypoglycemia (continued). "His mental status returned to baseline following administration of intravenous dextrose and 100 mg of octreotide, a drug that inhibits insulin release and is used as an antidote for recurrent hypoglycemia associated with sulfonylurea toxicity." (PMID 32555139, 2020). "Of importance to glycemic control in T2DM, GLP-1 acts on the islet β-cell GLP-1R to potentiate insulin secretion in a glucose-dependent manner, greatly reducing the risk for hypoglycemia compared to other insulin secretagogues." (PMID 33364978, 2020). "Insulin-glargine is a well-known long-acting insulin analog that is given for basal insulinization with a lower risk of hypoglycemia." (PMID 32498358, 2020). "The CHI diagnosis was either clinical or by the alternative, p-insulin-free criteria; hypoglycemia plus disease-causing genetic mutations and/or CHI-compatible pancreatic histopathology." (PMID 33679602, 2020). "The most common neurological complications associated with insulin therapy are those related to insulin-induced hypoglycemia, such as confusion, blurred vision, and, in extreme cases, epilepsy, and coma." (PMID 32982980, 2020). "Giving a standard (i.e. full) insulin bolus correction before a prolonged aerobic exercise event is not recommended unless ketones are elevated, since doing so increases hypoglycaemia risk." (PMID 32533229, 2020). "Persistent ketonuria after resolution of hyperketonemia can lead to unnecessary additional insulin administration as the result of a misguided desire to rapidly “clear” the urine ketones and can cause hypoglycemia." (PMID 32256447, 2020). "For instance, insulin-naive women initiating a basal insulin regimen showed a smaller improvement in HbA1c associated with an increased rate of hypoglycaemia vs men." (PMID 31754750, 2020). "Reducing nutrition (and thus insulin) thus reduces risk of hypoglycaemia, further emphasising this “workload-performance-nutrition” risk and reward trade-off." (PMID 32349750, 2020). "Insulin degludec achieves a steady-state in 2–3 days and exhibits lower day-to-day variability in glucose-lowering effect compared to insulin glargine, with a relatively lower risk of hypoglycaemia." (PMID 32290465, 2020). "Elevated outpatient insulin and C-peptide levels associated with fasting hypoglycemia confirmed the clinical diagnosis of insulinoma." (PMID 32605595, 2020). "Our results are therefore probably indicative of the increasing use of insulin analogues than of an increased risk of hypoglycaemia during this treatment." (PMID 32704570, 2020). "Other systems, such as the synchronisation of the blood glucose sensor and the continuous closed-loop insulin infusion pump, also prevent the risk of hypoglycemia and improve patients’ quality of life." (PMID 32143452, 2020). "Another method of insulin delivery, IV administration, in AD patients has showed improved memory performance, but long-term treatment poses a risk of hypoglycemia." (PMID 33100956, 2020). "Reductions in medication load would be welcome for any patient with a long-term condition, and the reduction in sulphonylurea use and total daily dose of insulin is likely to lead to reduction in hypoglycaemia risk and incidence." (PMID 32832564, 2020). "The limited risk-reducing effects from insulin treatment have been attributable to the low compliance issues caused by subsequent weight gain and episodes of hypoglycemia." (PMID 33195459, 2020). "In about one‐third of the patients in our series, the only cause of hypoglycaemia identified was overdose of insulin or sulphonylurea, which was corrected in the ER." (PMID 32704570, 2020). "In diabetic individuals, hypoglycemia is most commonly caused by administering insulin or sulphonylureas and insulin secretagogues." (PMID 34394252, 2020).
Hypoglycemia (continued). "Congenital hyperinsulinism (CHI), a disorder of heterogeneous aetiology characterised by dysregulated and inappropriate insulin secretion, is a significant cause of hypoglycaemia in neonates and infants with the potential for permanent neurologic injury." (PMID 32027664, 2020). "This was associated with increased plasma insulin levels, hypoglycemia, and improved glucose tolerance, while isolated islets had an increased second-phase insulin secretion." (PMID 32395123, 2020). "In our setting, the use of a sensitive insulin assay gave a diagnostic performance of the p-insulin concentration during hypoglycemia with AUC=1.0 in all ROC-curve analyses and 100% sensitivity and specificity in diagnosing CHI." (PMID 33679602, 2020). "The aim of this study was to observe glycemic control, insulin dosing, and hypoglycemia risk in patients switched to V-Go in a real-world setting." (PMID 31833010, 2020). "This study demonstrated that closed-loop insulin delivery was associated with comparable glucose control and significantly less hypoglycemia than SAP therapy." (PMID 33153229, 2020). "Congenital Hyperinsulinism (HI) is a genetic disorder of the pancreatic β-cells that causes dysregulated insulin secretion and persistent hypoglycemia." (PMID 32735622, 2020). "TZDs and DPP-4is were both associated with similar risks of MACEs and hypoglycemia but a lower risk of all-cause mortality than basal insulin (TZDs: HR 0.55, 95% CI 0.38–0.81; DPP-4is: HR 0.56, 95% CI 0.39–0.82)." (PMID 32238842, 2020). "Physiological insulin therapy with insulin analogs is now relatively simple to use and is associated with fewer episodes of hypoglycemia in diabetics." (PMID 32506749, 2020). "Further studies need to be conducted to identify the optimum insulin regimen to use and the frequency of blood glucose monitoring to avoid hypoglycemia in patients with those risk factors." (PMID 32133264, 2020). "Attention should be paid to weight loss, which increases insulin sensitivity and vulnerability to hypoglycemia." (PMID 33139628, 2020). "Hyperinsulinemia (insulin iAUC0’-45’), with plasma insulin peak levels twice higher in the Hypo group, was a risk for hypoglycemia during MMTT (binary logistic regression: p=0.042)." (PMID 33424773, 2020). "Insulin has been widely used for decades in critically ill hospitalized patients with DM and the usage of continuous glucose monitoring reduces the rates of hypoglycemia associated with insulin use." (PMID 33584268, 2020). "Very tight glucose control using insulin has been associated with an increased risk of hypoglycemia, and prophylactic insulin has been associated with increased mortality." (PMID 33306685, 2020). "Infants born SGA have decreased glycogen and fat stores, inappropriate release of insulin, and impaired counter regulatory hormones, leading to increased risk of neonatal hypoglycemia." (PMID 32117839, 2020). "This combination also allows a reduced insulin dosage, lessens the risk of insulin-induced hypoglycaemia, and reduces weight gain." (PMID 33746742, 2020). "By definition, if a PNET produces insulin in sufficient amounts to cause hypoglycemia, that PNET is considered an “insulinoma”9." (PMID 33060578, 2020). "In a recent review article, it was recommended to lower the amount of insulin to reduce the risk of hypoglycemia and to monitor hypoglycemia for up to 6 hours after insulin use in patients with chronic kidney disease." (PMID 32149451, 2020). "It has now been demonstrated that treatment with Sulfonylureas provide a better metabolic equilibrium than insulin by normalizing the HbA1c while strongly reducing the incidence of hypoglycemia in cases of neonatal diabetes with ABCC8 or KCNJ11 mutations." (PMID 33102403, 2020). "It is well established that sulphonylureas (e.g., glibenclamide) cause hypoglycemia by stimulating insulin release from pancreatic β-cell." (PMID 32207527, 2020).
Hypoglycemia (continued). "Treatment of hyperkalemia with intravenous insulin-dextrose is associated with a risk of hypoglycemia." (PMID 33328554, 2020). "These are typically small (1–2 cm3), slowly proliferating, benign, beta-cell tumors that overproduce insulin, thereby causing hypoglycemia, seizures, and/or episodes of unconsciousness." (PMID 33060578, 2020). "Intranasal insulin avoids the risk of hypoglycemia and bypasses insulin resistance due to direct delivery to the CNS, thus is a more sustainable long term treatment." (PMID 33100956, 2020). "Technosphere insulin is associated with lower risk of hypoglycemia and weight gain compared with insulin aspart, but dry cough 10 min after inhalation has been described by 24–33% of patients." (PMID 32344939, 2020). "With the addition of three independent variables including total treatment time ≥ 7 days, FBG < 7 mmol/L, and fasting insulin ≤ 9.30 mu/L, the risk of hypoglycemia gradually increased." (PMID 33015194, 2020). "In conclusion, the risk of hypoglycaemia is lower with once-daily basal insulin than conventional or intensified insulin therapy." (PMID 32316649, 2020). "Despite the benefits of treatment with 4 U/day insulin, it is known that chronic insulinization increases the risk of hypoglycemia." (PMID 32566072, 2020). "Insulin secretagogues such as sulfonylureas are associated with a high risk of hypoglycemia among diabetics." (PMID 32656029, 2020). "Repaglinide is another medication which can improve GV by promoting insulin release from the pancreas with a low risk of developing hypoglycemia." (PMID 33072435, 2020). "Congenital hyperinsulinism is characterized by abnormal regulation of insulin secretion from the pancreas causing profound hypoketotic hypoglycemia and is the leading cause of persistent hypoglycemia in infants and children." (PMID 33108363, 2020). "The barriers to initiating insulin include misconceptions about insulin, perceived difficulty in management for both physicians and patients, and risk of hypoglycemia and weight gain." (PMID 32406854, 2020). "For individuals using MDI, the basal insulin dose can be reduced by 20–50% before exercise to mitigate hypoglycaemia risk." (PMID 32533229, 2020). "While basal insulin remains the most effective antidiabetic agent and substantially reduces the risk of hypoglycemia, few studies have examined the comparative effect of basal insulin in the real-world setting." (PMID 32238842, 2020). "DANA is also expected to be useful as a glucose-dependent insulin secretagogue that has a low risk of hypoglycaemia." (PMID 32251344, 2020). "Other available data comparing Gla-300 vs. NPH insulin provide consistent results regarding hypoglycaemia risk but variable findings with respect to HbA1c." (PMID 32337298, 2020). "Both in vitro and in vivo studies showed that insulin release responded quickly to elevated glucose concentrations, and a single patch can modulate BGLs effectively avoiding the risk of hypoglycemia." (PMID 32325974, 2020). "According to the results of a meta-analysis, insulin had significantly higher risk of neonatal hypoglycemia than metformin." (PMID 33403188, 2020). "The combination of GLP-1RA and basal insulin has verified efficacy in lowering blood glucose and has extra advantage in weight control and lower risk of hypoglycemia." (PMID 32267843, 2020). "There are current therapy options for T2DM management such as sulphonylureas, glinides and insulin therapy, whereas these antidiabetic medications have an increased risk of hypoglycaemia, obesity and oedema." (PMID 33126761, 2020). "Among oral antidiabetic drugs, users of sulfonylurea (SU) drugs and insulin are more likely to cause severe hypoglycemia in older adults, which leads to dementia, low ADL, incident cardiovascular disease, and increased mortality." (PMID 33139628, 2020).
Hypoglycemia (continued). "With regard to the various antidiabetic agents used in advanced DKD patients, sulfonylurea, glinide, and insulin were found to be associated with higher risks of hypoglycemia in the present study." (PMID 30934740, 2019). "The most common cause of hypoglycemia is misuse of medications such as insulin and sulfonylureas to control blood glucose levels." (PMID 31052436, 2019). "Because activation of these receptors augments insulin secretion only when glucose levels are elevated, they can be targeted therapeutically to raise insulin levels with minimal risk of iatrogenic hypoglycemia." (PMID 31498851, 2019). "The DPP-4 inhibitors have neutral effects on body weight or risk of hypoglycemia (justified by the glucose-dependent insulin secretion mode of action of GLP-1), except when there is concomitant treatment with insulin or sulfonylureas." (PMID 31366085, 2019). "These real-world studies demonstrated that degludec was associated with improved glycemic control and reduced hypoglycemia rates compared with previous basal insulin treatment." (PMID 31397845, 2019). "It decreases after food intake, constituting a peripheral negative feedback and increase after weight loss, in fasting condition and insulin induced hypoglycemia." (PMID 31191339, 2019). "Psychological distress was recorded as the most prevalent barrier to insulin initiation across the region and risk of hypoglycaemia the least prevalent; weight gain was considered secondary to quality of life as a barrier to insulin initiation." (PMID 30993528, 2019). "Many hybrid and fully closed‐loop insulin delivery systems have been limited by the degree of aggressiveness with which RAIAs can be used to control PPG because of the risk of late hypoglycaemia." (PMID 31144428, 2019). "This was a significant concern for PwDM on anti-diabetic medications such as insulin injections with a risk of hypoglycaemia." (PMID 31139011, 2019). "Short-acting insulin analogues (aspart, glulisine, and lispro) were associated with a 32% lower risk rate of severe hypoglycemia when compared with regular human insulin (risk rate 0.68, 95% CI 0.60–0.77; 5945 patients, 15 studies; I2 = 0%)." (PMID 30622653, 2019). "Accompanied by the widespread use of a non-invasive glucose monitoring system, nocturnal hypoglycemia and its mortuary risk have been investigated in diabetic patients treated with insulin therapy." (PMID 30658460, 2019). "Further investigation to identify the cause of hypoglycaemia revealed that insulin and C-peptide were inappropriately raised." (PMID 31839727, 2019). "Multivariate analysis revealed hemodialysis compared with peritoneal dialysis, stroke, use of sulfonylurea, glinide, and insulin were associated with higher risk of severe hypoglycemia one year after transitioning to dialysis." (PMID 30934740, 2019). "An increased risk for hypoglycemia was however observed, when Empa, Cana or Dapa were added on treatment with insulin or SU." (PMID 31426529, 2019). "Low GI snacks consumed before bedtime have also been shown to reduce the risk of nocturnal hypoglycemia following exercise, due to delayed and enduring glycemic effects and lower rapid insulin requirements." (PMID 31835538, 2019). "Hemodialysis compared with peritoneal dialysis, stroke, use of insulin, sulfonylurea, and glinide were associated with higher risk of severe hypoglycemia in the critical transition period." (PMID 30934740, 2019). "If this result is combined with the previous report that the risk for hypoglycemia is higher in insulin users, it seems that strict blood glucose control by insulin therapy increases the risk of hypoglycemia." (PMID 30815039, 2019). "After admission, a 5 h-OGTT showed a blood glucose level of < 3 mmol/L, an insulin level of > 3 mU/L and a C-peptide level of > 0.6 ng/mL, with supporting hypoglycemia caused by excessive endogenous insulin." (PMID 31852474, 2019).